BRAF (B-Raf proto-oncogene, serine/threonine kinase)
Diseases named in the same sentence as BRAF in open-access papers (continued):
Sharing a sentence is not in itself a finding about the gene and the disease.
melanoma (continued). "We chose NRAS over BRAF because there is more frequent CDH1 downregulation in NRAS-mutant melanomas and a lack of targeted therapies for NRAS-mutated cases." (PMID 40500450, 2025). "BRAF inhibitors in BRAF mutant melanoma have a response rate of approximately 50% to 70%." (PMID 40869231, 2025). "However, based upon the results of the DREAMseq study, BRAF-mutant melanoma patients should first be treated with ICI, and if they progress, BRAF/MEK inhibitors can be highly successful." (PMID 40904502, 2025). "Furthermore, another study revealed that PERK plays a crucial role in mediating resistance to BRAF inhibition in melanoma, particularly in cases where PTEN function is impaired." (PMID 40129883, 2025). "We retrospectively analyzed 49 advanced BRAF-mutant melanoma patients treated with BRAFi/MEKi." (PMID 41294692, 2025). "In BRAF inhibitor-resistant melanoma cell lines, ABCB5 is overexpressed, indicating its role in resistance mechanisms, although it may not be a primary targetable contributor." (PMID 40867277, 2025). "Studies of melanoma cells with BRAF V600E mutations showed that CDK4 mutations alone did not significantly affect response to BRAF inhibitors." (PMID 40332392, 2025). "In particular, oridonin shows great potential for combination strategies, such as pairing with immune checkpoint inhibitors or BRAF inhibitors, which could enhance overall treatment efficacy for malignant melanoma while delaying the emergence of resistance." (PMID 40599859, 2025). "Similarly, in BRAF-mutant melanomas, PAK1 activation drives resistance by engaging the AKT signaling pathway." (PMID 40001545, 2025). "Indeed, mutations in BRAF are prominent in melanoma, and inhibition of BRAF is a common, standard therapy for the treatment of BRAF-mutant melanoma." (PMID 41309533, 2025). "Similarly, BRAF inhibitor resistance decreases melanoma antigen expression owing to MAPK reactivation." (PMID 40058234, 2025). "Given their lower BRAF mutation rates and the limited efficacy of current ICI treatments, these findings emphasize the urgent need for optimize immunotherapy strategies in Japanese melanoma patients." (PMID 40192945, 2025). "Here, we used this approach to further study resistance to BRAF inhibition in BRAFV600E melanoma." (PMID 39856157, 2025). "Ideally, this biomarker could be used additionally in decision-making for BRAF-mutated melanoma between ICI and BRAF or MEK inhibitor treatment, and contribute to the further optimization of personalized medicine in dermatological oncology." (PMID 40940903, 2025). "Mutations in the RAS/BRAF axis system, especially NRAS, are common in sinonasal melanomas, often even more common than other common melanoma mutations such as BRAF." (PMID 41369373, 2025). "Another study revealed that tumor biopsies from patients with metastatic melanoma undergoing treatment with a BRAF inhibitor, who progressed on therapy, showed a significant decrease in melanoma antigen expression at the time of progression through reactivation of the MAPK pathway." (PMID 40058234, 2025). "Similarly, miR-99b~125a~let-7e expression levels were high in melanoma cell lines with acquired resistance to BRAF/MEK inhibitors, showing upregulation of immunosuppressive cytokines." (PMID 41550951, 2025). "Moreover, FAO modulates the response of BRAF-mutant melanoma cells to MAPK pathway inhibitors, thereby contributing to therapeutic resistance and disease progression." (PMID 40721981, 2025). "Approximately 15–20% of melanomas have mutations in NRAS, while ~6% have normal BRAF." (PMID 40558548, 2025).
melanoma (continued). "Therefore, the objective of this study is to evaluate the association between antibiotic exposure and clinical outcomes in patients with advanced BRAF-mutant melanoma treated with BRAFi/MEKi." (PMID 41294692, 2025). "Within advanced unresected melanoma, NRAS or BRAF mutation has little effect on ICI response." (PMID 40362630, 2025). "Lastly, the TWT melanoma subtype is characterized by the absence of mutations in the three most common melanoma driver genes, namely BRAF, NRAS, and NF1." (PMID 40867277, 2025). "Age-standardized net survival analysed melanoma-specific mortality by BRAF genotype." (PMID 40902091, 2025). "Patients with high-risk GEP results may benefit from adjuvant immune checkpoint inhibitors (nivolumab and pembrolizumab) or targeted therapies (BRAF/MEK inhibitors in BRAF-mutant melanoma)." (PMID 40282456, 2025). "This allows melanoma cells to maintain growth and resist the effects of BRAF/MEKi." (PMID 40872623, 2025). "Early-onset melanomas, which typically occur in middle-aged adults at sites with low cumulative sun damage (CSD), often harbor somatic BRAF or NRAS mutations, are associated with a higher number of nevi, and are primarily linked to intermittent UV exposure during childhood." (PMID 39941357, 2025). "For the melanoma cohort, 78% of patients had a diagnosis of cutaneous melanoma with BRAF wild type status (BRAF is the most commonly altered genetic alteration in melanoma and used for treatment decisions), and most patients were treated with combination anti-PD-1 and anti-CTLA-4." (PMID 40217292, 2025). "There are also differences in subtypes and mutation patterns in paediatric melanoma compared to adult melanoma, such as the relatively higher incidence of Spitzoid melanomas and the relative lack of BRAF V600E and TERT promoter mutations." (PMID 40926920, 2025). "Consistently, HK2 depletion decreased SOX10 protein levels, but not SOX10 mRNA levels, in four different BRAF-mutated (V600E) melanoma cell lines." (PMID 40956859, 2025). "The treatment landscape for advanced melanoma has transformed significantly with the advent of BRAF and MEK inhibitors (BRAF/MEKi) targeting BRAFV600 mutations, as well as immune checkpoint inhibitors (ICI) like anti-PD-1 monotherapy or its combinations with anti-CTLA-4 or anti-LAG-3." (PMID 39859576, 2025). "Moreover, the presence of these deletions in BRAF wild type model melanoma samples suggested a significant shift in understanding the mechanisms behind the generation of BRAF transcript variants that contribute to resistance in melanoma." (PMID 40872623, 2025). "In BRAF-mutant melanoma, heterogeneous MET expression allows for HGF-driven resistance." (PMID 40332392, 2025). "Recently a new genomic alteration about inhibitor BRAF resistance in melanoma emerged." (PMID 40872623, 2025). "Similarly, the responsiveness of melanoma brain metastases to ICIs and BRAF‐targeted therapy challenges traditional assumptions about the impermeability of the blood‐brain barrier." (PMID 40653940, 2025). "BRAF V600E mutations are found in multiple tumor types, and BRAF inhibitors in combination with MEK inhibitors are part of the standard of care (SOC) in BRAF-mutant melanoma and non-small cell lung cancer." (PMID 39863775, 2025). "In particularly difficult cases, molecular analysis may be helpful; TMMs are known to exhibit highly similar mutational landscapes to conventional melanomas (e.g., mutations in NF1, NRAS; variable BRAF V600E)." (PMID 40090763, 2025). "Three BRAF inhibitors are used to treat melanoma and colorectal cancer." (PMID 41249187, 2025). "For example, PERK mutations in human melanomas have inhibitory functions on PERK activity, and reducing PERK expression by 50% in a BRAF-dependent mouse melanoma model promoted the development of BrafV600E-induced tumors, although complete loss of PERK was tumor suppressive." (PMID 39951426, 2025). "BRAF V600K melanomas were downregulated for module 1 (RPS15, RPL29, RPL10)." (PMID 39796775, 2025).
melanoma (continued). "Notably, pharmacologic inhibition of GPX4 or glutathione synthesis has been shown to restore ferroptosis sensitivity and resensitize melanoma cells to BRAF-targeted therapy." (PMID 40909289, 2025). "Strategies used to overcome resistance in BRAF–mutant melanoma, such as the development of next-generation targeted drugs and combination therapies to inhibit multiple signaling pathways, could be adapted for PCP." (PMID 40696244, 2025). "Similarly, driver mutations in the BRAF gene can form NSCLC, anaplastic thyroid cancer, and melanoma." (PMID 40943615, 2025). "Class I mutations were almost exclusively found in melanomas and were always accompanied by co-driver MAPK mutations, predominantly in BRAF or NRAS, and may contribute to aggressive melanoma behaviour." (PMID 40107205, 2025). "The model distinguishes 3 lines of systemic treatment for melanoma with a BRAF mutation and 2 lines of systemic treatment for melanoma without a BRAF mutation." (PMID 39985400, 2025). "Melanomas often develop concurrent resistance to BRAF and MEK inhibitors." (PMID 40135438, 2025). "In addition, current and ongoing clinical trials have focused on agents targeting the PI3K/AKT/mTOR pathway in metastatic and BRAF-mutant melanoma." (PMID 40399946, 2025). "Furthermore, drug combinations targeting lipid metabolism, such as inhibiting cholesterol acetylation (ACAT/SOAT), can enhance the sensitivity of melanoma cells to BRAF inhibitors by inducing ferroptosis." (PMID 40652057, 2025). "ICIs such as anti-PD-1 antibodies are broadly effective across melanoma subtypes regardless of BRAF mutational status and have substantially improved survival." (PMID 40981345, 2025). "In patients with stage III BRAFV600-mutant melanoma, adjuvant BRAF/MEKi therapy has shown activity." (PMID 39859576, 2025). "This includes 29 patients with breast cancer (14 tested positive for HER2), 13 with malignant melanoma (5 tested positive for the BRAF-V600E mutation), 1 with NSLSC (no PD-L-1 mutation), and 1 with esophagus cancer (no PD-L-1 mutation)." (PMID 40994525, 2025). "The cytotoxicity of complexes 2 was evaluated in vitro by determining the half inhibitory concentrations (IC50) against four human cell lines: wild-type BRAF melanoma (MeWo), lung adenocarcinoma (A549), bladder cancer (T24), and non-cancerous skin keratinocytes (HaCaT)." (PMID 40244013, 2025). "Mutation of BRAF is found in more than half of melanomas, and results in hyperactivation of the BRAF/MEK/ERK signaling pathway, which is involved in multiple cellular processes, including melanoma cell proliferation and survival." (PMID 39970778, 2025). "Furthermore, combining these drugs with either BRAF or MEK inhibitors resensitizes melanoma cells to the latter and enhances xenograft tumor growth inhibition." (PMID 40721981, 2025). "We found multiple hotspots and driver mutations in the BRAF/MEK/PI3K pathway, which are crucial for tumor progression, growth, survival, and therapy resistance in CRC and other tumors like melanoma and breast cancer, due to abnormal kinase activation and pathways." (PMID 41009348, 2025). "It was shown that for the whole population of patients with BRAF V600-mutated melanoma there was no statistically significant OS benefit of adjuvant TT versus placebo (hazard ratio (HR) for death, 0.80; 95 % confidence interval [CI], 0.62 to 1.01; p = 0.06)." (PMID 39673834, 2025). "Immunophenotypic silence: the absence of classic melanoma markers (e.g., BRAF mutation, mitosis) does not preclude aggressive behavior, as supported by recent molecular profiling studies." (PMID 41346450, 2025). "The study encompassed both in vitro and in vivo experiments, utilizing BRAF-mutant melanoma cell lines A375 and SK-MEL-28 treated with valsartan alone or in combination with vemurafenib, as well as immunocompromised mice xenografted with A375 cells receiving the same treatment regimens." (PMID 41301459, 2025).
melanoma (continued). "In addition, BRAF inhibition has been found to induce adaptive autophagy in BRAF-mutant melanoma, which facilitates tumor cell survival under therapeutic pressure." (PMID 40909289, 2025). "For example, although SBDD enabled the development of vemurafenib for BRAF V600E-mutant melanoma, rapid emergence of resistance driven by MAPK pathway reactivation or alternative mutations highlights the ongoing gap between structural prediction and durable clinical efficacy." (PMID 41209584, 2025). "Our data show that a substantial fraction of BRAF‐mutated human melanomas either do not express or express low amounts of LKB1." (PMID 39115053, 2025). "Recent advances in the treatment of malignant melanoma, such as B-Raf proto-oncogene serine/threonine kinase (BRAF) and mitogen-activated extracellular signal-related kinase (MEK) inhibitors and immune checkpoint inhibitors, have improved the overall survival of the patients." (PMID 39828865, 2025). "Also, we evaluated the impact of CB-839 on decreasing melanoma resistance to single targeted therapy, both in vitro and in vivo (BRAF mouse model)." (PMID 40943167, 2025). "Transitions were estimated separately for melanoma with and without a BRAF mutation and for patients with favorable and intermediate prognostic factors." (PMID 39985400, 2025). "Similar to observations in BRAF V600E mutated melanoma, no increase in pMEK was observed in M121224 and M170917 after mirdametinib treatment alone." (PMID 41199020, 2025). "Comprehensive molecular profiling, including common melanoma-associated mutations in BRAF, NRAS and the GNAQ/GNA11 signaling pathway, was not performed in this case." (PMID 41294657, 2025). "Furthermore, in melanoma, BRAF plays a crucial role in this metabolic reprogramming due to its significant effect on glucose metabolism through various mechanisms." (PMID 40872623, 2025). "A low‐molecular‐weight BRAF inhibitor, vemurafenib, has been shown to inhibit MAPK signalling, specifically in melanoma harbouring the BRAFV600E mutation, resulting in an antiproliferative action against malignant tumour cells in individuals diagnosed with cutaneous melanoma." (PMID 40817681, 2025). "Of new cases of melanoma, 14% (n = 13 138/91 415) had a BRAF test registered." (PMID 40902091, 2025). "Another key anti-apoptotic protein, Mcl-1, plays a particularly important role in BRAF-mutant melanomas; in these tumors, MAPK pathway hyperactivation drives both increased MCL1 transcription and stabilization of Mcl-1 protein through phosphorylation at threonine 163, preventing its degradation." (PMID 40721981, 2025). "Moreover, inhibition of CSNK2A1 in combination with BRAF inhibitors has a lethal synergistic effect by reducing AKT signaling in melanoma and thyroid cancer cells." (PMID 39820173, 2025). "As Spitz melanoma is classified as a non-CSD melanoma and most frequent and exclusive mutations are represented by BRAF and NRAS mutations in melanoma, the molecular profiling becomes even more important in terms of diagnosis and prognosis." (PMID 40870546, 2025). "Therefore, blocking BRAF kinase function with BRAF inhibitors reduces glycolysis and induces oxidative phosphorylation, which is promising in preventing melanoma progression." (PMID 40617808, 2025). "In addition to surgical treatment of early-stage melanoma, the standard of care for melanoma today consists of immune checkpoint inhibitors (e.g., pembrolizumab, nivolumab, and ipilimumab) and BRAF/MEK inhibitors." (PMID 40937999, 2025). "In addition, the use of a BRAFi in combination with OXPHOS inhibitors such as phenformin and gossypol suppressed melanoma cell proliferation indicating that OXPHOS was dependent on the inhibition of the BRAF/MEK/ERK signaling pathway." (PMID 39970778, 2025).
melanoma (continued). "Here, we demonstrate that genetic or therapeutic targeting of the PREX2/RAC1/p110β pathway can substantially enhance responses to MAPK targeting in BRAF-mutant melanoma both in vitro and in vivo, presumably through suppression of AKT/mTOR driven cell-cycle progression." (PMID 39636745, 2025). "Our previous studies demonstrated that 1H and 31P MRS could noninvasively monitor key metabolic parameters, including lactate, alanine, pH, and bioenergetics (βNTP/Pi), to capture the effects of single-agent BRAF or MEK inhibition in human melanoma models." (PMID 39984334, 2025). "Additionally, resistance mechanisms include the PI3K/AKT/mTOR pathway, which is dysregulated in 22% of BRAF inhibitor-resistant melanomas characterized by increased expression of the AKT protein." (PMID 39941158, 2025). "Treatment strategies are extrapolated from studies in cutaneous and unknown primary melanoma, with immune checkpoint inhibitors serving as the cornerstone of therapy in BRAF-wild-type, unresectable cases." (PMID 41384184, 2025). "IMspire150 (NCT02908672) was a randomized, double-blind, placebo-controlled phase 3 clinical trial that assessed vemurafenib and cobimetinib with or without atezolizumab in patients with metastatic BRAF-mutated melanoma." (PMID 40564107, 2025). "Furthermore, single-arm trials like RELATIVITY-047 and DREAMseq explored novel combinations, including LAG-3 and BRAF + MEK inhibitors for BRAF-mutant melanoma, showing encouraging response rates." (PMID 40001572, 2025). "Caspase-3/GSDME-dependent pyroptosis in BRAF-mutant melanoma." (PMID 41235238, 2025). "While this aberration is less locus-specific than the MITF amplification, BRAF is a well-described melanoma oncogene and thus this amplification could have also contributed to the progression of the disease." (PMID 41168392, 2025). "Therefore, in the present study, we evaluated the efficacy of two novel C‐terminal inhibitors in targeting chemo‐resistance pathways in melanoma cells resistant to BRAF‐ and MEK‐inhibitors." (PMID 40135438, 2025). "Combining BH3 analogs with BRAF/MEK inhibitors can boost apoptosis in melanoma cells." (PMID 40331942, 2025). "Targeting these miRNAs may represent a strategy to improve the efficacy of BRAF/MEKi therapy in melanoma patients by modulating the TME." (PMID 41550951, 2025). "This study also suggests multi-targeting compounds like SC-62-1 might be useful for overcoming resistance to BRAF inhibitors for improved melanoma treatment." (PMID 40649216, 2025). "For example, none of the five melanomas with a RASGRF fusion identified in this study had co-occurring activating BRAF or NRAS mutations." (PMID 40615519, 2025). "Furthermore, in patients with melanoma, BRAF positivity and prior treatment with BRAF-targeted therapies are both associated with a marked reduction in the response to ICIs." (PMID 41010951, 2025). "The high frequency of BRAF and NRAS mutations in particular provides important insights into the molecular heterogeneity of melanomas and potential sensitivity to targeted therapies, while NF1 and PTEN mutations further illustrate the diversity of driver alterations in this population." (PMID 41142596, 2025). "In advanced melanoma, ipilimumab 10 mg/kg improved median OS versus 3 mg/kg (15.7 vs. 11.5 months; HR 0.84, p = 0.04) and 5-year survival (25% vs. 19%), with benefits consistent across subgroups, including brain metastases and BRAF-mutant tumors." (PMID 41527622, 2025). "Targeted therapy should not be offered to patients with BRAF V600K-mutated melanoma in light of the potential detrimental effect on OS reported in the COMBI-AD trial [II, D]." (PMID 39550033, 2025). "Therefore, for patients with ALK-positive NSCLC and BRAF V600-mutant melanoma, HSP90 inhibitor-based combination therapy is a promising strategy to overcome resistance and enhance therapeutic outcomes." (PMID 40872476, 2025).